TSHR (thyroid stimulating hormone receptor)
Diseases named in the same sentence as TSHR in open-access papers (continued):
Sharing a sentence is not in itself a finding about the gene and the disease.
hyperthyroidism (continued). "We recently described a patient`s phenotype due to a TSHR mutation with comparable functional characteristics as non-autoimmune and non goitrous hyperthyroidism." (PMID 21835055, 2011). "Here we report a male infant with nonautoimmune hyperthyroidism due to an activating germline TSHR mutation (A623V), whose clinical picture started in the newborn period with severe hyperthyroidism." (PMID 21274318, 2010). "A persistent, nonautoimmune form of hyperthyroidism results from gain−of−function mutation in the TSHR gene." (PMID 21274318, 2010). "Although congenital nonautoimmune hyperthyroidism is rare, in patients with neonatal hyperthyroidism with negative antibodies, TSHR mutations should be included in the differential diagnosis." (PMID 21274318, 2010). "Diagnosing nonautoimmune hyperthyroidism due to activating TSHR mutation is of great importance for both patient management and genetic counseling." (PMID 21274318, 2010). "Here we report a case of sporadic congenital nonautoimmune hyperthyroidism with an activating TSHR germline mutation in a Turkish boy." (PMID 21274318, 2010). "Activating germline mutations in GNAS may cause McCune–Albright syndrome resulting in a multinodular toxic goiter, where activating germline mutation in TSHR causes nonautoimmune hyperthyroidism with or without nodular lesions within the thyroid." (PMID 39189533, 2025). "In humans, the role of distinct TSHR CAMs in the pathogenesis of hyperthyroidism remains unclear." (PMID 38194289, 2024). "The in vivo animal study demonstrates that mice with VD deficiency may develop persistent hyperthyroidism following immunization with thyroid-stimulating hormone receptor (TSHR), whereas mice with adequate levels of VD do not exhibit such symptoms." (PMID 39771102, 2024). "The clinical spectrum of thyrotropin receptor–mediated (TSHR-mediated) diseases varies from loss-of-function mutations causing congenital hypothyroidism to constitutively active mutations (CAMs) leading to nonautoimmune hyperthyroidism (NAH)." (PMID 38194289, 2024). "A recent meta-analysis of eight randomized clinical trials has shown that although probiotics and prebiotics did not change the level of thyroid hormones, they may modestly reduce thyroid-stimulating hormone receptor antibody levels in patients with hyperthyroidism." (PMID 39649015, 2024). "However, the precise mechanisms underlying the development of clinical hyperthyroidism and toxic thyroid nodules due to TSHR gain-of-function mutations is not comprehensively understood." (PMID 38194289, 2024). "TSHR variants associate with hypo- and hyperthyroidism but not with other phenotypes in FinnGen." (PMID 38194289, 2024). "However, no TSHR mutation has been found for hyperthyroidism in the city hospital-based cohort of KoGES." (PMID 37686882, 2023). "In addition, vitamin D-deficient BALB/c mice developed persistent hyperthyroidism after immunization with TSHR, not seen in vitamin D-sufficient mice." (PMID 28895880, 2017). "Therefore it might be that estimation of further molecular aspects of TSHR signal transduction should help to explain the variability in hyperthyroidism-phenotypes." (PMID 21835055, 2011). "Hyperthyroidism of non-autoimmune etiology is an uncommon occurrence, and its etiology may be the result of germline variants capable of activating the thyroid-stimulating hormone receptor (TSHR)." (PMID 41631090, 2026). "It is an autoimmune disorder, in which thyroid-stimulating hormone receptor autoantibodies (TRAb) stimulate the thyroid stimulating hormone (TSH) receptor, leading to hyperthyroidism." (PMID 40255503, 2025). "TED is mediated by antibodies targeting the thyroid-stimulating hormone receptor (TSHR) and the insulin-like growth factor-1 receptor (IGF1R), which leads to hyperthyroidism." (PMID 41227354, 2025).
hyperthyroidism (continued). "In GD, thyroidal T-cell infiltration and B-cell activation lead to the production of TSH-receptor autoantibodies (TRAb), whose binding to TSHR drives goiter, hyperthyroidism, and extrathyroidal manifestations such as ophthalmopathy and dermopathy." (PMID 41465179, 2025). "Thyroid-stimulating hormone receptor antibodies (TRAb) play a key etiological role in this process by stimulating thyroid-stimulating hormone (TSH) receptors, thereby leading to hyperthyroidism." (PMID 40095806, 2025). "The appearance of elevated TSHR-Ab serum levels (along with an increase in FT4 and FT3 levels) in patients with diffuse hyperthyroidism with normal TSHR-Ab levels suggests that the immune system has a secondary role in the etiology of GD." (PMID 38813368, 2024). "As the fetal TSHR is able to respond to TSH stimulation from 17–19WG, fetal hyperthyroidism develops during the second trimester, especially in women with high levels of TRAb." (PMID 37233673, 2023). "On the other hand, in GD the presence of thyroid-stimulating antibodies, which activate the thyrotropin receptor (TSHR) on thyrocytes, leads to thyroid hyperplasia and, finally, hyperthyroidism." (PMID 36981758, 2023). "TSHR can co-locate with IGF-1R on thyroid cells and orbital fibroblasts to activate subsequent hyperthyroidism and GO." (PMID 35462920, 2022). "GD is believed to represent the autoimmune process of the thyroid, in which irritant autoantibodies combined with the thyroid-stimulating hormone receptor (TSHR) and activate thyroid function, leading to hyperthyroidism." (PMID 35059400, 2021). "Of these, TSHR is a thyroid-specific gene and CTLA-4 is an immunoregulatory gene affecting GD development, both of which are related to the pathogenesis of hyperthyroidism." (PMID 31565653, 2019). "Afterwards, thyroid-stimulating immunoglobulin (TSI) antibodies bind with thyroid-stimulating hormone receptor (TSHR) in the thyroid and result in the proliferation of thyrocytes and the development of hyperthyroidism." (PMID 31252621, 2019). "As an organ-specific autoimmune disease, GD is usually characterized by the presence of circulating autoantibodies that bind to TSHR on thyrocytes and mimic the effects of TSH, resulting in hyperthyroidism and goiter." (PMID 31341471, 2019). "This includes the apparent central importance of TSHR and TSI in development of both hyperthyroidism and ocular manifestations of the disease." (PMID 29744034, 2018). "Consistent with the extreme degree of hyperthyroidism, the qualitative balance in the BXA13 strain was almost entirely towards functional TSHR antibodies, with minimal ELISA-positive antibodies." (PMID 21738647, 2011). "In some patients, the initial manifestation of the constitutively active TSHR mutation is hyperthyroidism without any increase in the gland mass, whereas in others, goiter development may precede the onset of the clinical findings of hyperthyroidism." (PMID 21274318, 2010). "Third, the TSHR-induced hyperthyroidism mouse model, while useful for studying GD, does not fully replicate the complexity of human GD." (PMID 41010493, 2025). "To date, there have been few reports of dupilumab-associated autoimmune endocrine disorders, such as painless thyroiditis accompanied by hypothyroidism, type 1 diabetes, and hyperthyroidism with negative TSHR-Ab." (PMID 40895907, 2025). "This implies that different types of TSHR antibodies in patients with AITD may undergo transformation, akin to the two sides of a coin, where hyperthyroidism can convert to hypothyroidism and vice versa." (PMID 39872521, 2024). "Autoantibodies to the thyrotropin receptor (TSHR) resemble TSH, resulting in hyperthyroidism." (PMID 37910311, 2024). "Familial nonautoimmune hyperthyroidism (FNAH) and Sporadic nonautoimmune hyperthyroidism (SNAH) are two types of activating TSHR germline mutations." (PMID 37233673, 2023).
hyperthyroidism (continued). "There were even studies showing that hyperthyroidism was not even observed in BALB/c mice immunized by intramuscular injection of an expression vector constructed from human TSHR cDNA." (PMID 35813642, 2022). "Pharmacologic suppression of endogenous TSH via the negative feedback loop for the purpose of inhibiting TSHR-mediated growth signaling often leads to subclinical hyperthyroidism." (PMID 32698392, 2020). "His thyroid function prior to pembrolizumab administration had been subclinical hyperthyroidism, despite a negative thyroid-stimulating hormone receptor antibody (TRAb) level." (PMID 31772785, 2019). "In contrast, no mice of the same strain injected with wild-type TSHR DNA vaccine showed TSAbs and hyperthyroidism." (PMID 27895620, 2016). "This form of hyperthyroidism differs from GD in that occurs in women without a past history of GD and in the absence of detectable TSHR-Ab." (PMID 27981252, 2016). "In patients with GH, decrease in serum TPO and Tg antibody titres correlated with both a fall in TSHr antibody levels, when measured (results not shown), and improvement in hyperthyroidism, manifested by need for reducing doses of antithyroid medication." (PMID 26798548, 2015). "Because TSIs rather than TSH activate TSHR in GD and drive hyperthyroidism, these mAbs (M22, 2 μg/mL) were tested and found to induce IL-6 after 16 h by 22- and 46–fold in fibroblasts and fibrocytes, respectively (both p<0.001)." (PMID 24086448, 2013). "TSHR represents the primary autoantigen in hyperthyroidism of GD [Brand and Gough, 2010], so is unlikely to be involved in HT." (PMID 24227294, 2013). "First, extreme thyroid hyperplasia and hyperthyroidism in one AXBXA strain likely reflects its inability to generate ELISA-type TSHR antibodies ot the type not observed in Graves' patients." (PMID 21738647, 2011). "Clinical guidelines do not currently specify appropriate use of TSHR autoantibody tests in the diagnosis of hyperthyroidism, which may result in paired orders for both tests with the possibility of discordant results and excessive costs." (PMID 40482060, 2025). "Additionally, a pediatric case documented the onset of hyperthyroidism during dupilumab therapy, despite the lack of positive TSHR-Ab." (PMID 40895907, 2025). "Therefore, in such patients, other clinical manifestations should be investigated to identify the essence of diffuse hyperthyroidism when TSHR-Ab levels are not elevated." (PMID 38813368, 2024). "Further inquiry revealed that her hyperthyroidism had been diagnosed 18 months prior without any relevant symptoms, and approximately 5 months prior, she was diagnosed with GD with high levels of thyroid-stimulating hormone-receptor antibodies (TSH-R-Ab) and thyroglobulin (Tg) at that time." (PMID 38968474, 2024). "However hTSHR/NOD.H2h4 mice do not develop hyperthyroidism, because the antibodies target human TSHR and do not cross react with the mouse TSHR." (PMID 35572553, 2022). "However, even immunization of mice with purified murine TSHR ectodomain expressed in insect cells with an adjuvant failed to induce hyperthyroidism." (PMID 27895620, 2016). "First, extreme thyroid hyperplasia and hyperthyroidism in one remarkable strain, BXA13, reflected an inability to generate non-functional TSHR antibodies measured by ELISA." (PMID 21738647, 2011). "Intriguingly, immunizing mice with fibroblasts transfected with either TSHR or MHC class II alone did not induce Graves’ hyperthyroidism, indicating that aberrant expression of MHC class II molecules on cells expressing a native form of the TSHR can induce TSAb production." (PMID 27895620, 2016).
thyroid cancer (140 papers, 2005 to 2025). "In contrast to the situation in thyroid cancer, high expression of TSHR in other tumor types is closely associated with malignant progression and poor prognosis, likely due to distinct activation states and regulatory pathways in these tumors." (PMID 40532044, 2025). "Dedifferentiation is a common feature of thyroid cancer and is often accompanied by a decrease in TSHR expression, which is typically associated with increased tumor invasiveness and poor prognosis." (PMID 40532044, 2025). "We discuss how mtDNA alterations disrupt oxidative phosphorylation (OXPHOS), trigger adaptive metabolic rewiring, and interact with key oncogenic pathways, such as HIF-1α, BRAFV600E mutations, and TSHR signaling in thyroid cancer." (PMID 41301693, 2025). "TSHR, a thyroid cell-specific marker, is also implicated in the metabolic regulation of thyroid cancer." (PMID 41301693, 2025). "Evaluating TSHR expression in thyroid cancer organoids holds promise for addressing the issue of TSHR loss in cell lines." (PMID 40532044, 2025). "In summary, HIF-1α, BRAF mutations, and TSHR signaling synergistically contribute to metabolic plasticity in thyroid cancer, representing key mechanisms underlying metabolic reprogramming and drug resistance." (PMID 41301693, 2025). "From another perspective, the activating mutations of either TSHR or Ga proteins that underlie functioning thyroid nodules preclude thyroid cancer." (PMID 39061242, 2024). "Further research is needed to elucidate the precise molecular mechanisms underlying TSHR methylation, the role of sex hormones, and the impact of genetic and environmental factors on the development and progression of thyroid cancer." (PMID 39125979, 2024). "Among the 16 TSHR mutation positive patients with available histology, 3 patients had evidence of thyroid cancer." (PMID 33632297, 2021). "Taken together, TSHR has a growth-promoting or oncogene-like function in thyroid cancer, although other co-existing mutations are required to establish a fully malignant phenotype." (PMID 32698392, 2020). "Except for the TSH-induced activation of TSHR, there are numerous spontaneously occurring mutations located within the TSHR gene, which are identified in thyroid cancer patients." (PMID 32698392, 2020). "The activated TSHR-induced signaling cascades have been shown to serve as oncogenic pathways in thyroid cancer, especially in tumors carrying mutations at V600E in B-Raf proto-oncogene." (PMID 32698392, 2020). "While activating somatic mutations of TSHR have been found in up to 84% of toxic thyroid nodules, they are rare in malignant thyroid tumors." (PMID 33383892, 2020). "In this work, we conducted the first diagnostic meta-analysis to draw a system evaluation for TSHR-mRNA on the diagnosis of thyroid cancer." (PMID 28036261, 2017). "As a potential diagnostic biomarker for thyroid cancer, serum or plasma TSHR-mRNA is characterized by minimal invasion and convenience compared with FNA based histopathological examination." (PMID 28036261, 2017). "The association between well-differentiated thyroid carcinomas and TSHr methylation status was previously studied using formaldehyde-fixed paraffin-embedded thyroid tissues or thyroid cell lines." (PMID 26519197, 2015). "Hypermethylation of TSHR may be associated with specific miRNA dysregulation, affecting the development and progression of thyroid cancer." (PMID 39125979, 2024). "The association between germline variants of TSHR and cancer risk is unclear although a few of studies suggest that certain TSHR polymorphism may increase the risk of thyroid cancer." (PMID 37885353, 2024). "This study may provide greater insights into the differentiation features associated with TSHR expression in thyroid cancer, and Kir5.1 may be a potential therapeutic target in the redifferentiation strategies for recurrent and metastatic thyroid cancer." (PMID 37208644, 2023).
thyroid cancer (continued). "Mutations of Gsa subunit and the TSHR gene rarely occur in well-differentiated thyroid cancers." (PMID 28117293, 2017). "Our meta-analysis suggests that TSHR-mRNA might be a potential biomarker to complete present diagnostic methods for early and precision diagnosis of thyroid cancer." (PMID 28036261, 2017). "However, a system evaluation of TSHR-mRNA as a diagnostic biomarker for thyroid cancer is deficient, so we made this first diagnosis meta-analysis of TSHR-mRNA on thyroid cancer." (PMID 28036261, 2017). "Moreover, Graves’ disease, an autoimmune disorder characterized by the presence of TSH receptor stimulating antibodies (TSHR-Abs) has been found to be associated with increased thyroid cancer risk and thyroid cancer aggressiveness." (PMID 24115945, 2013). "Both loss and gain of function TSHR mutations are often found in thyroid cancer." (PMID 21781349, 2011). "Thus, it seems that enhanced TSHR signaling due to some rare TSHR-activating mutations could lead to thyroid cancer development and growth." (PMID 39061242, 2024). "TSHR expression has been reported to be associated with unfavorable prognosis in other cancers, such as liver cancer, but whether this is also the case in thyroid cancer remains unknown." (PMID 34650915, 2021). "However, few TSHR mutations in thyroid cancer tissue have been reported." (PMID 34650915, 2021). "Based on prior reported cases and experimental studies, TSHR mutations, especially those occurring with a high allelic frequency (>30%) and/or at specific codons (e.g., between 620 and 631), are associated with the uncommon but relatively increased risk of functioning thyroid carcinomas." (PMID 30319546, 2018). "Moreover, studies on the commonalities between these two cancers may provide new prophylactic therapeutic strategies and early diagnostic methods, such as anti-estrogen therapy for thyroid carcinoma and anti-TSHR therapy for breast carcinoma." (PMID 29976206, 2018). "However, system evaluation for TSHR-mRNA as a diagnostic biomarker of thyroid cancer is deficient." (PMID 28036261, 2017). "A comprehensive assessment of the absolute expression level of TSHR on the cell surface of patient-derived thyroid cancer cells is essential for understanding its potential role in tumor progression and therapeutic targeting." (PMID 40532044, 2025). "Clinical trials with adequate anticipation should investigate anti-TSHR CAR-T as a potential treatment option for individuals with local recurrence or distant metastasis of thyroid cancer." (PMID 40007813, 2025). "In summary, TSHR-targeted imaging and therapeutic agents demonstrate high specificity and sensitivity for thyroid cancer diagnosis." (PMID 40532044, 2025). "Lysine residues in TR1401 are replaced with arginine residues to create TR1402 for a further increase in affinity for TSHR, particularly in thyroid cancer cell lines." (PMID 40532044, 2025). "These nanoparticles can target thyroid cancer cells expressing TSHR through interaction with TSH, increasing treatment specificity and reducing the cardiotoxicity of doxorubicin." (PMID 40532044, 2025). "On the basis of these findings, a patient with recurrent, refractory thyroid cancer was recruited and received TSHR + CD19 CAR-T-cell therapy; this patient achieved partial remission within 3 months and tolerated the treatment well." (PMID 40532044, 2025). "The results showed that TSH‐CAR‐T cells specifically target TSHR‐positive tumor cells and effectively control tumor growth in in vitro co‐culture experiments with thyroid cancer cells as well as in mouse tumor models." (PMID 40985353, 2025). "In this study, we identified thyroid‐stimulating hormone receptor (TSHR) as a promising antigen for CAR‐T cell therapy in thyroid cancer." (PMID 40985353, 2025). "Studies assessing the differences in TSHR levels on KAT-5 cells revealed that downregulation of TSHR expression weakly inhibited thyroid cancer cell proliferation but significantly increased metastasis." (PMID 40532044, 2025).